UPF3B (UPF3B regulator of nonsense mediated mRNA decay)
Diseases named in the same sentence as UPF3B in open-access papers (continued):
Sharing a sentence is not in itself a finding about the gene and the disease.
neurodevelopmental disorder (9 papers, 2015 to 2025). A behavioral and cognitive disorder with onset during the developmental period that involves impaired or aberrant development of intellectual, motor, or social functions. "The functional relevance of the poorly characterized mid‐domain of the UPF3 proteins is further underscored by several missense UPF3B mutations that fall within this domain in individuals with neurodevelopmental disorders." (PMID 35451102, 2022). "Here we demonstrate using tethered function assays that missense mutations associated with neurodevelopmental disorders alter the function of UPF3B protein in mRNA metabolism." (PMID 26012578, 2015). "Using tethered function assays we found that UPF3B missense mutations described in families with neurodevelopmental disorders reduced the activity of UPF3B protein in NMD." (PMID 26012578, 2015). "Together, these experiments demonstrate that mutations in UPF3B linked to neurodevelopmental disorders impair the activity of UPF3B protein in NMD." (PMID 26012578, 2015). "Together these experiments indicate that differentiating neural stem cells are able to undergo UPF3B-promoted NMD, and that NMD in these cells is sensitive to UPF3B protein variants found in subjects with neurodevelopmental disorders." (PMID 26012578, 2015). "Several independent missense mutations in UPF3B have been reported in patients with neurodevelopmental disorders." (PMID 26012578, 2015). "In contrast, the number and complexity of branches was reduced significantly in cells expressing UPF3B proteins encoded by genes with mutations occurring in neurodevelopmental disorders." (PMID 26012578, 2015). "Importantly, the structure of the UPF2-3B complex comprised UPF3B residue Y160 which was reported to be mutated to aspartate (Y160D) in patients with neurodevelopmental disorders." (PMID 35551602, 2022). "Analysis of cells after three and six days of differentiation revealed that the number of branches per cell was reduced two-fold in the presence of Amlexanox, similar to the effect of the expression of UPF3B proteins encoded by genes with mutations occurring in neurodevelopmental disorders." (PMID 26012578, 2015). "We therefore wished to establish whether the expression of the UPF3B protein variants found in patients with neurodevelopmental disorders affects neuronal differentiation." (PMID 26012578, 2015). "Similarly, UPF3B inactivating mutations in humans are non‐lethal but cause intellectual disability and are associated with neurodevelopmental disorders such as autism spectrum disorders and schizophrenia." (PMID 35451102, 2022). "Missense mutations in UPF3B found in patients with neurodevelopmental disorders may contribute to the development of these disorders by an impairment of UPF3B activity in the NMD process that results in aberrant gene expression affecting neuronal differentiation." (PMID 26012578, 2015). "The levels of both paralogs appear to be tightly regulated and are of paramount importance during neurodevelopment, as evidenced by UPF3B mutations leading to decreased NMD efficiency and neurodevelopmental disorders in affected families." (PMID 35551602, 2022). "For instance, loss-of-function mutations in UPF2, UPF3B, SMG8 and SMG9 genes, and CNVs targeting UPF2, UPF3A, SMG6, EIF4A3, RNPS1 and RBM8A genes, have been implicated in a variety of neurodevelopmental disorders, including DD, ID, ADHD and TAR syndrome." (PMID 35327467, 2022). "The neuronal differentiation of neural stem cells was disturbed by the expression of UPF3B proteins from patients with neurodevelopmental disorders." (PMID 26012578, 2015). "Tethering of UPF3B proteins found in patients with neurodevelopmental disorders resulted in three- to five-fold higher Renilla luciferase activity than when wild type UPF3B protein was tethered." (PMID 26012578, 2015).
neurodevelopmental disorder (continued). "The GSE99112 was excluded because the Upf3b-mutant mouse did not demonstrate hyperlocomotion and seems to be a model for the other neurodevelopmental disorders rather than ADHD." (PMID 41303563, 2025). "In summary, the expression of UPF3B proteins found in patients with neurodevelopmental disorders, but not wild type UPF3B protein, disturbs neuronal differentiation, specifically the branching of neurites." (PMID 26012578, 2015).
cancer (8 papers, 2015 to 2025). A tumor composed of atypical neoplastic, often pleomorphic cells that invade other tissues. "Mutations in NMD factors (in particular UPF3B) and NMD dysregulation can be associated with neurodevelopmental disease and cancer." (PMID 36979701, 2023). "First, several cancers lack a control group, further investigating the expression and function of UPF3B using a large sample size is necessary." (PMID 36194583, 2022). "The results also revealed correlations of UPF3B expression with diverse cancer patients’ clinical prognoses." (PMID 36194583, 2022). "In the present study, we synthetically explored the expression status and prognostic significance of UPF3B, and the relationship with clinic characters and immune microenvironment across cancers." (PMID 36194583, 2022). "Because we found that UPF3B was aberrantly expressed in several cancers and correlated with tumor progression, the correlation analysis of the UPF3B expression and clinical outcomes across different cancers was conducted in the TCGA cohort." (PMID 36194583, 2022). "UPF3B expression in 33 cancers versus counterpart normal tissues was analyzed using TCGA pan-cancer data." (PMID 36194583, 2022). "In our analysis, we comprehensively investigated the expression of UPF3B and their prognostic value in pan-cancer through bioinformatic analysis." (PMID 36194583, 2022). "Although UPF3B is less well-studied, we found several studies about additional UP-frameshift proteins in cancers." (PMID 33193701, 2020). "Our results may provide novel insights for UPF3B as an immunotherapeutic target and valuable prognostic biomarker in various malignant tumor." (PMID 36194583, 2022). "However, the role of UPF3B in cancer genomes consisting of its relationship with tumorigenesis, early diagnosis, prognosis, and therapy wasn’t supported by studies." (PMID 36194583, 2022). "In the present study, we investigated the mRNA levels of UPF3B and asked whether UPF3B abnormal expression was prognostic for patient survival each tumor using TCGA pan-cancer data." (PMID 36194583, 2022). "Proteomic data of UPF3B in cancer was got from UALCAN (contains 10 cancer protein expression data)." (PMID 36194583, 2022). "The transcriptional level of UPF3B was dysregulated in the human pan-cancer dataset." (PMID 36194583, 2022). "However, the clinical relevance of UPF3B in cancer patients, such as with prognosis, tumor stage, and levels of tumor-infiltrating immune cells remain unclear." (PMID 36194583, 2022). "Based on the RNA sequencing data in TCGA, we first evaluated the expression profiles of UPF3B across various types of cancers (including those cancers without normal tissues for comparison)." (PMID 36194583, 2022). "UPF3B has been identified as a potential treatment for NMD-induced diseases, including cancers." (PMID 34257547, 2021). "However, the role of UPF3b in cancer has not yet been reported and needs further study." (PMID 33251144, 2020).
tumor (4 papers, 2018 to 2024). "The difference in UPF3B mRNA and protein levels in different tumor types may reflect the distinct underlying functions and mechanisms." (PMID 36194583, 2022). "The influence of UPF3B in long-term prognosis was evaluated using Kaplan–Meier method, and the associations between UPF3B transcription levels and immune-related gene expression, immune cell infiltration, tumor microenvironment (TME) score are analyzed by spearman correlation analysis." (PMID 36194583, 2022). "The more biological function and molecular mechanisms of UPF3B in tumor progression were also intensively explored." (PMID 36194583, 2022). "We proceeded to analyzed the correlation of UPF3B expression with tumor stage and found that UPF3B expression significantly correlated with tumor stage in ESCA and LIHC." (PMID 36194583, 2022). "Third, more in vivo and in vitro experiments should be done to test the antitumor activity by targeting UPF3B and the role in regulating tumor immune microenvironment." (PMID 36194583, 2022). "Collectively, these results all indicate that expression of UPF3B is closely related to immune infiltration of tumor cells, affects patient prognosis in multiple tumors, providing a potential target for immunotherapy." (PMID 36194583, 2022). "Immunohistochemical staining results displayed that NOL3 and UPF3B were upregulated in CRC tumor tissues." (PMID 33193701, 2020). "UPF3B was significantly upregulated in patients with deeper tumor infiltration, as well as late clinical stage." (PMID 33193701, 2020). "The results indicated that NOL3 and UPF3B were overexpressed in CRC tumor tissues compared with normal tissues." (PMID 33193701, 2020). "In KICH and SKCM, the UPF3B expression elevated slightly but significantly with higher tumor stage." (PMID 36194583, 2022). "We further investigated the effect of UPF3B on the tumor microenvironment (TME)." (PMID 36194583, 2022). "Expression levels for NMD-related factors (UPF1, UPF2, UPF3A, UPF3B, SMG1, SMG2, SMG6, and SMG7) were calculated from microarray-derived datasets of primary tumor samples (n = 40 MSI, n = 48 MSS) and matched normal colon samples (n = 95)." (PMID 30228267, 2018).
neurodegenerative disease (1 paper, 2024). A disorder of the central nervous system characterized by gradual and progressive loss of neural tissue and neurologic function. "UPF3BY160D significantly inhibits both the interactions of UPF3B with IRE1α and UPF2, suggesting that the missense mutation of UPF3B loses its suppressive function in IRE1α activation, potentially leading to chronic UPR activation for the development of some neurodegenerative diseases." (PMID 39138189, 2024).
neurological disorders (1 paper, 2022). "A better understanding of the extent to which UPF3A functions synergize or antagonize those of UPF3B is also necessary to understand the basis of UPF3B‐caused human neurological disorders." (PMID 35451102, 2022).
UPF3B also shares sentences with these, for which no sentence is quoted: cholangiocarcinoma (3 papers); Stomach Adenocarcinoma (3); Thyroid Carcinoma (3); X-linked intellectual disability (3); attention deficit-hyperactivity disorder (2); Bladder Urothelial Carcinoma (2); Breast invasive carcinoma (2); childhood onset schizophrenia (2); colon adenocarcinoma (2); developmental delay (2); gastric cancer (2); head and neck squamous cell carcinoma (2); lung adenocarcinoma (2); lung carcinoma (2); Lung Squamous Cell Carcinoma (2); ovarian carcinoma (2); pancreatic adenocarcinoma (2); sarcoma (2); alcoholic hepatitis (1); autism spectrum disorder (1); Barrett esophagus (1); blood tumor (1); brain cancer (1); breast carcinoma (1); cervical cancer (1); Colon cancer (1); Ductal Breast Carcinoma (1); embryonal carcinoma (1); endometrial carcinoma (1); esophageal squamous cell carcinoma (1).
A further 22 diseases each share a sentence with UPF3B in 1 paper.